TRAJ22 (T cell receptor alpha joining 22)
Gene: T-cell receptor joining (J) gene on chromosome 14 (22,522,040 to 22,522,102, forward strand). Ensembl gene ENSG00000211867.
Diseases named in the same sentence as TRAJ22 in open-access papers:
TRAJ22 is named in the same sentence as 1 disease in open-access papers, as found by Europe PMC text mining. Sharing a sentence is not in itself a finding about the gene and the disease.
TRAJ22 shares sentences with these, for which no sentence is quoted: Allergy (1 paper).